TLR4 (toll like receptor 4)
Diseases named in the same sentence as TLR4 in open-access papers (continued):
Sharing a sentence is not in itself a finding about the gene and the disease.
breast cancer (continued). "Furthermore, expression of TLR4 and its downstream adapter protein MyD88 was found to be significantly higher in breast cancer than adjacent normal tissues, which was associated with poor prognosis." (PMID 36765715, 2023). "Indeed, after radiotherapy, breast cancer patients with a compromised HMGB1 engagement by TLR4 undergo relapses more rapidly than patients bearing normal TLR4 alleles." (PMID 36831435, 2023). "This indirect mechanism is noticeably distinct from the direct effect of resistin on breast cancer cells, such as the enhanced tumor growth and metastatic ability of breast cancer cells via toll-like receptor 4 (TLR4) or adenylyl cyclase-associated protein 1 (CAP1)-mediated pathways." (PMID 36104403, 2022). "In breast cancer, TLR4 activation has been linked to both cancer inhibition and growth." (PMID 33733435, 2021). "TLR4 was a prognostic biomarker in breast cancer and associated with poor prognosis." (PMID 34707562, 2021). "Furthermore, breast cancer patients with a TLR4 loss‐of‐function allele, that prevents HMGB1 binding to TLR4, are more prone to relapse after radiotherapy or chemotherapy." (PMID 33179413, 2020). "Both TLR4, expressed on APC, and HMGB1 are required for ICD and for efficient immune stimulation as demonstrated in experiments neutralizing HMGB1 and in breast cancer patients having a loss-of-function TLR4 allele exhibiting reduced binding affinity for HMGB1." (PMID 29462947, 2018). "The proinflammatory stimuli, LPS binding to TLR4 was shown to cause breast cancer cell invasion." (PMID 28212583, 2017). "However, little is known about the underlying mechanism by which LPS/TLR4 regulates breast cancer progression involving migration, invasion or metastasis." (PMID 28212583, 2017). "Because several studies implicated a correlation between TLR4 expression and breast cancer progression, including proliferation and invasiveness, we decided to perform initial cell proliferation studies by cultivating the cells in the presence of different concentrations of the TLR4 ligand LPS." (PMID 26863029, 2016). "TLR4-MyD88 signaling pathway activation or MyD88 activation alone may be a risk factor for poor prognosis in breast cancer." (PMID 25360699, 2014). "Moreover, patients with breast cancer who carry a TLR4 “loss-of-function” allele relapse more quickly after radiotherapy and chemotherapy than those carrying the normal TLR4 allele." (PMID 23378947, 2013). "Interestingly, patients with breast cancer who are treated with chemotherapy and radiotherapy and carry a TLR4 loss-of-function allele relapse faster than those carrying the normal TLR4 allele." (PMID 22891162, 2012). "Furthermore, a recent study showed that samples of breast carcinomas with recurrence exhibit a significant increase in the mRNA levels of TLR4 and that TLR4 expression is significantly associated with a great rate of distant metastasis." (PMID 22195048, 2011). "Moreover, as TLRs ligands, LPS was reported to increase breast cancer metastasis in vitro and in vivo, and acquiring of high metastatic potential upon the TLR4-elicited activation of NF-κB in breast cancer cells was associated with integrin αvβ3, TPM1 and maspin." (PMID 33363472, 2020). "Our work provides new insight into the development/progression of inflammation and breast cancer, suggesting that activation of the TLR4-MyD88 signaling pathway or MyD88 alone may be risk factors for a poor breast cancer prognosis and may be novel targets for the development of biomodulators." (PMID 25360699, 2014). "TOPK mediates lipopolysaccharide (LPS)-induced migration and invasion of breast cancer cells by activating the TLR4 signaling pathway, which increases TOPK expression." (PMID 41362722, 2026). "Elevated levels of TOPK and TLR4 in high-grade breast cancer tissues further support their involvement in tumor progression, positioning TOPK as a promising therapeutic target for inflammation-driven cancer metastasis." (PMID 41362722, 2026).
breast cancer (continued). "In general, these data showed that exosomal SP1 played an indispensable role in activating the TLR4‐NFκβ‐IL‐1β pathway of neutrophils, thereby promoting lung metastasis of breast cancer." (PMID 39630109, 2025). "Berberine is a regulator of the HMGB1- Toll-like receptor 4 (TLR4) axis and can inhibit breast cancer metastasis aggravated by chemotherapy." (PMID 40490812, 2025). "HMGB1 enhances tamoxifen resistance in breast cancer cells by binding to TLR4 and activating the NF‐κB signaling pathway." (PMID 41354099, 2025). "Recent studies have shown that small EVs derived from F. nucleatum can also promote proliferation and migration of breast cancer cells by activating TLR4." (PMID 41597595, 2025). "CpdA targets this pathway, attenuating TLR-4-mediated PTX resistance in breast cancer and melanoma by inhibiting IL-6, IL-8, and XIAP, thus enhancing PTX sensitivity." (PMID 40404908, 2025). "In breast cancer, tumor-derived autophagosomes activate the TLR4‒MyD88 signaling pathway in ECs to upregulate PD-L1 expression, directly inhibiting T-cell function." (PMID 40521189, 2025). "In contrast, 40% of the nude mice inoculated with breast cancer cells transfected with TLR-4 silencing plasmids remained tumor-free." (PMID 40404908, 2025). "It has been found to protect against breast cancer tumorigenesis via the Toll-like receptor 4 (TLR4)/nuclear factor kappa B (NF-κB) pathways and to suppress colorectal cancer by inducing apoptosis and inhibiting glycolysis." (PMID 40822971, 2025). "Importantly, as previously noted, hyperoside can enhance the sensitivity of breast cancer cells to the conventional chemotherapy drug paclitaxel, an effect mediated by the inhibition of pro-inflammatory and pro-survival mechanisms associated with TLR4 activation." (PMID 40098612, 2025). "After ceasing PTX treatment, nearly all nude mice inoculated with breast cancer cells transfected with TLR-4 overexpression plasmids experienced tumor recurrence in a short time." (PMID 40404908, 2025). "It is noteworthy that LPS, a major component of the outer membrane of Gram-negative bacterial cell walls, can induce EMT by downregulating the Akt/GSK3β/β-catenin pathway via TLR2 and TLR4, thereby increasing the invasiveness of breast cancer." (PMID 41597595, 2025). "LPS up-regulates S100A7 expression in breast cancer cells, which in turn regulates TLR4 and RAGE expression, influencing breast tumorigenesis." (PMID 40666174, 2025). "Pharmacological inhibition of HMGB1 by CDK4/6 inhibitors has been also shown to present a powerful tool to overcome breast cancer resistance to tamoxifen by disrupting the TLR4-NF-κB pathway." (PMID 41465435, 2025). "A recent study demonstrated that breast cancer cells exhibit upregulated TLR4 expression during metastasis, enabling LPS to promote epithelial-mesenchymal transition through NF-κB-mediated ZEB1 activation." (PMID 40444051, 2025). "AGEs increased the expression of TLR4 and enhanced the activation of NF-κB in breast cancer cell line MDA-MB-231 cells." (PMID 41369400, 2025). "Since HMGB1 is overexpressed in breast cancer, TLR4 and AGER assessment offers a broader mechanistic perspective into innate immune activation and damage-associated inflammation, reinforcing the rationale for focusing on these markers." (PMID 40647480, 2025). "For the rest of the evaluated cell lines, a possible resistant mechanism is active as described in human breast cancer, like the overexpression of TLR4 (toll-like receptor-4), overexpression of RNF8 (finger protein 8), and overexpression of HER2, among others." (PMID 40646890, 2025). "The elevated expression of TLR3, TLR4, and TLR9 is associated with poorer survival in breast cancer patients." (PMID 41597595, 2025). "Although some studies have reported the relationship between TLR4 and clinicopathologic features and survival indicators of breast cancer, their conclusions are inconsistent." (PMID 38463226, 2024).
breast cancer (continued). "From the perspective of the relationship between TLR4 expression and clinicopathological features, a total of ten studies, including 1175 breast cancer patients, analyzed the relationship between TLR4 expression and lymph node metastasis." (PMID 38463226, 2024). "TLRs are a widely studied group of pattern recognition receptors; among them, TLR4 has been extensively studied and is known to be involved in the development of several types of tumors, such as breast cancer." (PMID 38725852, 2024). "For instance, the level of TLR4 expression can serve as a novel determinant of the response to paclitaxel in breast cancer." (PMID 38903515, 2024). "TLR4 has emerged as a promising therapeutic target in breast cancer due to its role in promoting tumor growth and progression." (PMID 38903515, 2024). "TLR4 and MyD88 protein expression levels are positively correlated with axillary lymph node metastasis and histological grade, and the co-expression of TLR4 and MyD88 is also positively correlated with breast cancer cell metastasis." (PMID 38347830, 2024). "Clinically, TLR4 overexpression serves as an independent predictor of poor disease-free survival in breast cancer patients." (PMID 38903515, 2024). "Similar TLR4 and NF-κB activation has been reported in breast cancer cells stimulated by bacterial LPS, leading to the expression of inflammatory factors and apoptotic proteins." (PMID 39926112, 2024). "Increased expression of TLR4 has been consistently observed in both breast cancer cells and tissues compared to their normal counterparts." (PMID 38903515, 2024). "The involvement of TLR4 in breast cancer cell signaling has been highlighted, particularly focusing on the role of LPS/TLR4 signaling in breast cancer development." (PMID 38903515, 2024). "Small extracellular vesicles derived from F. nucleatum in breast cancer facilitate tumor growth and metastasis via TLR4 signaling." (PMID 39926112, 2024). "Recently, TLR4 has been described to be highly expressed in diverse types of cancer, including colon cancer, hepatocarcinoma, ovarian cancer, lung cancer, and breast cancer, promoting inflammation, tumor growth, invasion, and metastasis of cancer cells." (PMID 38990440, 2024). "Taxol directly binds to and activates Toll-like receptor-4 (TLR4), which is often overexpressed on the surface of breast cancer cells, and induces a number of pro-inflammatory regulators that promote distant metastasis." (PMID 38674115, 2024). "The signaling cascade involving TLR4 and MyD88 is understood to promote the development and spread of breast cancer, with its suppression being recognized as a promising treatment strategy for hepatocellular carcinoma and epithelial ovarian cancer." (PMID 39390599, 2024). "Studies indicate that estrogen can upregulate TLR4 expression, and conversely, activation of TLR4 enhances estrogen-mediated signaling, potentially fueling estrogen-driven breast cancer growth." (PMID 38903515, 2024). "Toll-like receptor 4 promotes the survival and invasiveness of breast cancer cells and ovarian cancer cells through the induction of cell proliferation and apoptosis resistance." (PMID 39770406, 2024). "TLR4 is overexpressed in breast cancer and TLR4 signaling, usually through endogenous ligands from the tumors, improved anti-tumor immunity." (PMID 39594997, 2024). "Previous studies have highlighted TLR4’s crucial role in tumor growth regulation in breast cancer and its correlation with cancer growth and metastasis." (PMID 39390599, 2024). "Polysaccharide peptide (PSP) acts by upregulating the TLR4-TIRAP/MAL-MyD88 signaling pathway in peripheral blood mononuclear cells (PBMCs) from breast cancer patients, inducing the secretion of IL-12, IL-6, and TNF-α, thus serving as an immune adjuvant." (PMID 38347830, 2024).
breast cancer (continued). "Both TLR4 and MyD88 protein expressions are positively correlated with breast cancer cell metastasis." (PMID 38347830, 2024). "The literature underscores the significant role of TLR4 in breast cancer development and progression, highlighting its potential as a therapeutic target in breast cancer therapy." (PMID 38903515, 2024). "TLR4 is overexpressed in the majority of clinical breast cancer samples and 68% of the examined BC lines." (PMID 38463226, 2024). "Researches were shown that direct injection of LPS into glioblastoma and colorectal cancer led to tumor regression and knocking down TLR4 increased tumor malignancy in a lung metastatic model deprived from breast cancer." (PMID 37553698, 2023). "This can be achieved by future studies utilizing techniques including siRNA to perform a specific knockdown of STIM1 and STIM2, which will enable researchers to identify the specific roles of these proteins in the TLR4-induced signaling of breast cancer cells." (PMID 37371732, 2023). "In human breast cancer cells, exogenous S100a9 promotes autophagy through the cell-membrane receptors TLR4 and RAGE." (PMID 37723445, 2023). "In breast cancer cells (MDA-MB-231 positive for TLR4), the presence of hyperoside increased apoptosis, decreased cell viability, and activated caspase-3, all of which made cancer cells more susceptible to the chemotherapy drug paclitaxel." (PMID 37743502, 2023). "For example, Paclitaxel activates the toll-like receptor 4 (TLR4), which is present on macrophages to recognize polysaccharides and it is also expressed by breast cancer cells." (PMID 37182144, 2023). "Blocking TLR4 signaling was shown to significantly improve the response to paclitaxel therapy in breast cancer." (PMID 37112730, 2023). "Various cell lines and tissue samples from patients with head and neck, esophageal, gastric, colorectal, liver, pancreatic, skin, breast, ovarian, cervical, and breast cancer were found to express high levels of TLR4." (PMID 36936437, 2023). "Using gastric cancer and breast cancer models, propolis targeted the inflammatory cascade by downregulating Toll-like receptor 4 (TLR-4), glycogen synthase kinase 3 beta (GSK3 β), and NF-κB signaling pathways." (PMID 36986549, 2023). "The results of studies on the effect of substances present in propolis extracts indicate that one of the pathways inhibiting the proliferation of breast cancers is the inhibition of the Toll-like receptor 4 (TLR4) signaling pathway." (PMID 36840233, 2023). "In particular, it was observed that the expression levels of TLR4 and MyD88 are related to the metastatic and invasive potential of the breast cancer cell type." (PMID 37822929, 2023). "In MDA-MB-231 breast cancer cells, TLR4 silencing reduced cell proliferation and secretion of the proinflammatory cytokines IL8 and IL6, which are known to contribute to immune evasion and resistance to immunotherapy." (PMID 37112730, 2023). "Aligned with our results, studies in breast cancer suggested that S100A8 is associated with tumor growth and invasion in breast cancer through the activation of the TLR4, RAGE, and NFκB pathways." (PMID 37174723, 2023). "Similar to breast cancer, the TLR4 signaling pathway was found to be involved in the polarization of M2b macrophages since its blockade impaired the upregulation of M2b markers in HCC." (PMID 37108657, 2023). "In breast cancer cells, TLR4 activation promotes the migration of these cells and induces the production of inflammatory cytokines and oncogenes such as IL-6 and VEGF." (PMID 37371732, 2023). "The LPS treatment and TLR4 activation induced other actions in the breast cancer cells, in addition to an increase in the production of inflammatory mediators." (PMID 37371732, 2023). "Collectively, the findings of our study indicated that inhibiting the SOCE pathway suppressed the TLR4-induced inflammation, migration, and proliferation of breast cancer cells." (PMID 37371732, 2023).
breast cancer (continued). "Nonetheless, our findings showed, for the first time, that inhibiting SOCE using BTP2 can successfully suppress the TLR4-induced production of several inflammatory genes in breast cancer cells." (PMID 37371732, 2023). "Systemic delivery of c-di-GMP and monophosphoryl lipid A (a TLR4 agonist)-encapsulated nanoparticles generated a significant antitumor effect in a breast cancer animal model." (PMID 37324951, 2023). "Like resistin, more research is needed to evaluate the role of NEFAs as ligands in the TLR4/NFκB signaling pathway for promoting breast cancer progression." (PMID 37626871, 2023). "Certainly, these results are preliminary and further investigation is warranted to delineate the specific roles that each protein in the SOCE pathway play in mediating the TLR4-induced inflammation and cancer progression of breast cancer cells." (PMID 37371732, 2023). "To investigate the role of TLR4 on EPS-mediated growth inhibition of breast cancer cells, we utilized a CRISPR/Cas9 knockout approach to delete TLR4 in T47D cells." (PMID 38074643, 2023). "For example, recent evidence suggests that TLR-4 is over-expressed in most clinical breast cancers and involved in breast cancer development and progression." (PMID 36142391, 2022). "This study calls for oncologist’s attention to the previously neglected breast cancer commensal microbiota and highlights the role of bacterial components and its associated LPS/S100A7/TLR4 signaling cascade in the breast tumor microenvironment." (PMID 33969603, 2022). "In contrast, we demonstrated that TLR4 stimulation reduces microglia-assisted breast cancer cell invasion." (PMID 36224342, 2022). "Breast cancer cell-derived exosomes were also reported to induce autophagy of breast cancer cells by transferring miR-1910-3p while gastric cancer cell-derived exosomes were found to induce the autophagy of neutrophils via HMGB1/TLR4/NF-κB signaling." (PMID 36428401, 2022). "TLR2, TLR3, and TLR4 as biomarkers of proinflammatory response were increased significantly in patients with inflammatory bowel disease and breast cancer." (PMID 35425840, 2022). "Lee’s group extracted phlorofucofuroeckol A from E. cava and observed the suppression of migration and invasion of MCF-7 and MDA-MB-231 breast cancer cell lines by the downregulation of Nf-κB activity and Toll-like receptor 4 (TLR-4) signalling." (PMID 35209235, 2022). "In summary, LPS sensitizes the therapeutic response of both triple-negative and ER+ breast cancer to IAP antagonist therapy by inducing rapid apoptosis of the cancer cells through TLR4- and MyD88-mediated production of TNFα." (PMID 36119107, 2022). "Numerous studies have reported the role of TLR4 as an oncogene in various cancers, including breast cancer, colon cancer and HCC." (PMID 37304412, 2022). "This is the first study, which reports that LPS increases S100A7 expression in breast cancer cells, which in turn attenuates the expression of TLR4." (PMID 33969603, 2022). "These markers are highly upregulated in M-LECP recruited to clinical breast cancers as was determined by their expression in TLR4+/CD11b+ TAMs, which were also positive for lymphatic markers Lyve-1, podoplanin (Pdpn), or Vegfr-3." (PMID 35442077, 2022). "With the compelling evidence on the association between inflammation and cancer, the involvement of TLR4 in tumor progression has been well recognized, such as in breast cancer, colorectal cancer and ovarian cancer." (PMID 35372062, 2022). "Both Chinese propolis and CAPE activated the executioner caspase 3 in LPS-stimulated breast cancer cells, likely induced either through the autophagy or suppression of TLR-4 signaling." (PMID 36142391, 2022). "FAM49B can also stimulate breast cancer cell proliferation and migration through the Rab10/TLR4 pathway." (PMID 36499755, 2022). "Especially, TLR4 protein was found to be involved in breast cancer development, and its overexpression negatively correlates with prognosis." (PMID 36359024, 2022).